MIER3 (MIER family member 3)
Description:
Transcriptional repressor.
Synonyms: FLJ35954; DKFZp686L09111; DKFZp781I1119
Tractability: PROTAC: ubiquitination databases record sites on it.
Gene: Protein-coding gene on chromosome 5 (56,919,602 to 56,971,675, reverse strand). Ensembl gene ENSG00000155545.
Subcellular location: Nucleus
Subcellular location (Human Protein Atlas): Nucleoplasm
Gene Ontology:
Molecular function: histone deacetylase activity; histone deacetylase binding; transcription corepressor activity
Biological process: negative regulation of transcription by RNA polymerase II
Cellular component: nucleoplasm; nucleus; protein-containing complex
Genetic constraint (gnomAD): Loss-of-function variants: 7 observed, 52.53 expected, observed/expected ratio (o/e) 0.13, 90% interval 0.075 to 0.25. The upper end of that interval is the gene's LOEUF score, 0.25, which puts it in group 1 of 6, group 1 being the genes least tolerant of losing a copy. Missense variants: 480 observed, 655.14 expected, observed/expected ratio (o/e) 0.73, 90% interval 0.68 to 0.79. Synonymous variants: 186 observed, 225.27 expected, observed/expected ratio (o/e) 0.83, 90% interval 0.73 to 0.93.
Homologues: Orthologues: chimpanzee MIER3 (99% identical), macaque MIER3 (99% identical), pig MIER3 (97% identical), dog MIER3 (96% identical), rabbit MIER3 (96% identical), rat Mier3 (93% identical), mouse Mier3 (93% identical), tropical clawed frog mier3 (73% identical), zebrafish mier3a (63% identical), zebrafish mier3b (60% identical), Caenorhabditis elegans T07F8.4 (19% identical), Drosophila melanogaster CG1620 (15% identical), and 1 more. Paralogues in human: MIER1 (41% identical), MIER2 (37% identical), MTA1 (21% identical), MTA2 (19% identical), MTA3 (18% identical).
Diseases named in the same sentence as MIER3 in open-access papers:
MIER3 is named in the same sentence as 7 diseases in open-access papers, as found by Europe PMC text mining. Sharing a sentence is not in itself a finding about the gene and the disease. The quoted sentences say what the papers report.
colorectal cancer (5 papers, 2017 to 2023). A primary or metastatic malignant neoplasm that affects the colon or rectum. "Here, we reported that MIER3 was significantly reduced in human primary colorectal cancer and was associated with CRC metastasis and poor prognosis." (PMID 28887525, 2017). "Furthermore, human MIER3 is reportedly lowly expressed in colorectal cancer cells, which may correlate with the degree of tumor differentiation, suggesting that MIER3 is closely associated with colorectal carcinogenesis." (PMID 37240242, 2023). "Moreover, we conducted rescue assays to determine whether Sp1 was involved in the MIER3 silencing-associated increases in colorectal cancer cell proliferation and invasion." (PMID 28887525, 2017). "A recent study showed that MIER3 expression was significantly reduced in colorectal cancer at the mRNA and protein levels and was negatively correlated with aggressive tumors and poor clinical outcomes." (PMID 34322151, 2021). "Our results revealed that MIER3 was differentially expressed in all six colorectal cancer cell lines." (PMID 28887525, 2017). "MIER3 was downregulated in colorectal cancer tissue compared to healthy colon mucosa." (PMID 33552987, 2020). "Moreover, MIER3 suppressed colorectal cancer progression and inhibited epithelial-mesenchymal transition." (PMID 33552987, 2020). "Moreover, overexpression of MIER3 could inhibit the aggressive behaviors of colorectal cancer in vivo and in vitro." (PMID 34322151, 2021). "However, the expression pattern and the role of MIER3 in the progression of colorectal cancer (CRC) have not yet been well characterized." (PMID 28887525, 2017).
breast carcinoma (4 papers, 2014 to 2023). "Breast cancer studies have revealed that MIER3 is highly expressed in breast cancer, suggesting that human MIER3 is closely associated with the development of breast cancer." (PMID 37240242, 2023). "MIER3 (mesoderm induction early response 3) gene has been suggested to be candidate breast cancer susceptibility gene." (PMID 25927456, 2015). "The most significantly associated SNP, rs702681 (OR 1.06 [95%CI 1.04–1.08]; P 3.9×10−10), is located in the 3'UTR of MIER3, close to the known breast cancer susceptibility gene MAP3K1." (PMID 25390939, 2014).
colorectal tumor (1 paper, 2017). "In comparison, we observed high levels of MIER3 expression in 35 of 142 (24.6%) colorectal tumor tissue samples." (PMID 28887525, 2017).
lymph node metastasis (1 paper, 2017). "The expression of MIER3 was significantly associated with differentiation (p = 0.038), clinical stage (p = 0.035), T classification (p = 0.029), lymph node metastasis (p = 0.029), and distant metastasis (p = 0.022) in patients with CRC." (PMID 28887525, 2017).
tumor (5 papers, 2017 to 2023). "Analysis of both our CRC cohort and R2 genomics expression datasets showed the downregulation of CTNNA1, HIGD2A and MIER3 (also in association with the severe features of the tumor), but also an evident positive correlation of expression with LINC00483." (PMID 33552987, 2020). "Low expression levels of MIER3 were significantly associated with advanced clinical disease stage, tumor T classification and poor survival in patients." (PMID 28887525, 2017). "Because mutations in tumor-associated genes often lead to gene expression disorders and dysfunction, we first evaluated the relationship between MIER3 expression and clinicopathological features of CRC." (PMID 28887525, 2017). "In our study, the mRNA and protein levels of MIER3 were significantly reduced in tumor tissues, and deep deletion was the most common type of MIER3 mutation in COAD." (PMID 34322151, 2021). "These different findings suggest that the specificity and complexity of MIER3’s function and related mechanisms vary in different tumor types." (PMID 28887525, 2017). "All the functional experiments also confirmed MIER3 as a tumor suppressor in the progression of CRC." (PMID 28887525, 2017). "Inhibition of endogenous MIER3 in SW620 cells significantly increased tumor growth and the expression of Ki-67 compared with that of the control." (PMID 28887525, 2017). "CTNNA1 and MIER3 have a well-known tumor suppressor function." (PMID 33552987, 2020). "In conclusion, our data suggested that MIER3 plays a potential tumor suppressor role in CRC progression and may be a potentially valuable clinical prognostic marker of this disease." (PMID 28887525, 2017). "We investigated CTNNA1, HIGD2A, and MIER3 expression in CRC biopsies compared to adjacent normal mucosa in order to confirm their downregulation in CRC observed by dataset screening: the three mRNAs showed a statistically significant downregulation in tumor tissues compared to normal mucosa." (PMID 33552987, 2020). "Upregulation of MIER3 expression significantly inhibited CRC cell proliferation, migration, and invasion in vitro and repressed tumor growth and metastasis in vivo." (PMID 33552987, 2020). "Moreover, the up-regulation of MIER3 expression significantly inhibited CRC cell proliferation, migration and invasion in vitro and repressed tumor growth and metastasis in vivo." (PMID 28887525, 2017). "Furthermore, comparative analyses indicated that MIER3 protein expression was significantly down-regulated in the 12 examined tumor samples paired with adjacent non-neoplastic mucosa tissues." (PMID 28887525, 2017).
cancer (4 papers, 2017 to 2025). A tumor composed of atypical neoplastic, often pleomorphic cells that invade other tissues. "Mesoderm induction early response 1, family member 3 (MIER3) serves as a candidate cancer susceptibility gene." (PMID 33942991, 2021). "Mesoderm induction early response 1, family member 3 (MIER3) has recently been identified as a potential cancer susceptibility gene." (PMID 28887525, 2017). "The effects of endogenous MIER3 inhibition on metastasis was also assessed after the nude mice had been injected with the cancer cells through the tail vein." (PMID 28887525, 2017). "MIER3, which regulates cell proliferation and apoptosis, when downregulated, could support cancer cell survival by bypassing normal growth controls." (PMID 41411347, 2025).
infection (1 paper, 2017). The state of being infected such as from the introduction of a foreign agent such as serum, vaccine, antigenic substance or organism. "Increased expression of MIER3 upon infection in the cell line HCT116 was confirmed by western blot (p < 0.001)." (PMID 28887525, 2017).